NEUROD1 (neuronal differentiation 1)
Diseases named in the same sentence as NEUROD1 in open-access papers (continued):
Sharing a sentence is not in itself a finding about the gene and the disease.
MODY (28 papers, 2009 to 2025). "The first reported MODY-associated variants in NEUROD1, PDX1, APPL1, and WFS1 were <1:20,000 frequency." (PMID 40779032, 2025). "A recent study conducted in Brazil described the first case of NEUROD1-MODY in Latin America and identified a novel frameshift mutation, demonstrating that research in countries with multiethnic populations can enhance current understanding of the epidemiology and pathogenesis of MODY." (PMID 33292863, 2020). "Interestingly, in this study population, utilizing the NGS we have identified MODY variants in NEUROD1, PDX1 and BLK genes in comparison to the more commonly reported HNF4A, GCK and HNF1A gene variants." (PMID 28095440, 2017). "A recent study in Brazil described the first case of NEUROD1-MODY in Latin America and identified a novel frameshift mutation, suggesting that studies in countries with multiethnic populations may improve the current understanding of the epidemiology and pathogenesis of MODY." (PMID 39902162, 2024). "Heterozygous variants in NEUROD1, PDX1, APPL1, and WFS1 have been implicated in MODY, but strong genetic evidence supporting causality is lacking." (PMID 40779032, 2025). "In this study, we used a large clinically suspected MODY cohort and population controls to assess the genetic evidence for NEUROD1, PDX1, APPL1, and WFS1." (PMID 40779032, 2025). "In summary, rare heterozygous variants in NEUROD1 and PDX1 are low-penetrance causes of MODY, while those in APPL1 and WFS1 lack robust genetic evidence for causality and should not be included in MODY testing panels." (PMID 40779032, 2025). "MODY is genetically heterogenous, with alterations in at least 14 different genes reported, including neurogenic differentiation 1 (NEUROD1), a transcription factor involved in pancreatic beta cell maturation and maintenance." (PMID 37855645, 2023). "Mutations in genes like pancreatic and duodenal homeobox 1 (PDX1, MODY4), hepatocyte nuclear factor 1 beta (HNF1B, MODY5) neurogenic differentiation 1 (NEUROD1, MODY6) and insulin (INS, MODY10) cause relatively rare forms of MODY." (PMID 26300908, 2015). "In all cases, we observed consistent results that APPL1 and WFS1 variants are not enriched in the MODY cohort, whereas NEUROD1 and PDX1 were at a level similar to RFX6." (PMID 40779032, 2025). "Moreover, we also detected variants in rare MODY-related genes, including NEUROD1 (MODY6), KCNJ11 (MODY13) and APPL1 (MODY14), among other MODY subtypes." (PMID 36613572, 2022). "MODY is monogenic diabetes caused by a single gene mutation of either HNF-1α, HNF-1β, HNF-4α, HNF-1β, glucokinase, PAK4, KLF11, neurogenic differentiation 1 (neuroD1), and insulin (INS)." (PMID 35956399, 2022). "The six major MODY-causing genes encodes hepatocyte nuclear factor 4α (HNF4α), HNF1α, glucokinase (GCK), pancreatic and duodenal homeobox 1 (PDX1), HNF1β, and neurogenic differentiation 1 (NEUROD1)." (PMID 34444990, 2021). "Alternatively, other genes implicated in the pathogenesis of MODY could be more frequent in these groups, such as HNF4A, insulin promoter factor-1 (IPF-1), HNF1B, NeuroD1 and others." (PMID 31576961, 2020). "The result raised suspicion of a rare form of MODY caused by variants in the NEUROD1 gene; however, the patient did not have clinical features of this form of MODY, which can be associated with neurological abnormalities such as sensory–neural deafness, visual impairment and developmental delay." (PMID 37855645, 2023). "MODY are also associated with mutations in the genes encoding transcription factors like, hepatic nuclear factor 4 alpha (HNF4A), HNF1 homeobox A (HNF1A), pancreatic and duodenal homeobox 1 (PDX1), HNF1 homeobox B (HNF1B) and neurogenic differentiation 1 (NEUROD1)." (PMID 22399922, 2010). "Although DKA is relatively rare, there are relevant reports, observed in some types of MODY, such as INS-, PDX1-, NEUROD1-, HNF1A- and HNF1B-MODY." (PMID 40303944, 2025).
MODY (continued). "To date, 14 disease genes for MODY are identified; most of them are transcription factors MODY1 (HNF4A), MODY3 (HNF1A), MODY4 (PDX1), MODY5 (HNF1B), MODY6 (NEUROD1/BETA2), MODY7 (KLF11), MODY8 (CEL), MODY9 (PAX4), MODY11 (BLK), and MODY14 (APPL1)." (PMID 31145732, 2019). "In conclusion, we provide genetic evidence that NEUROD1 and PDX1 cause low penetrance MODY whereas variants in APPL1 and WFS1 do not cause MODY and should not be included in MODY genetic analysis." (PMID 40779032, 2025). "Coding sequences of the genes causing MODY1-4 and MODY6 (GCK, HNF1A, IPF1, NEUROD1, and HNF4A) were sequenced in the proband to rule out known causes of MODY with compatible clinical presentations." (PMID 19216786, 2009).
small cell lung carcinoma (26 papers, 2020 to 2026). Small cell lung cancer (SCLC) is a highly aggressive malignant neoplasm, accounting for 10-15% of lung cancer cases, characterized byrapid growth, and early metastasis. "Small cell lung cancer (SCLC) is frequently subdivided into four molecular subtypes according to the activity of key transcription factors (TF): NEUROD1, ASCL1, POU2F3, and YAP1 (NAPY)." (PMID 41732133, 2026). "In small cell lung carcinoma, transcription factors such as NEUROD1, achaete-scute family bHLH transcription factor 1 (ASCL1), POU class 2 homeobox 3 (POU2F3), and Yes1-associated transcriptional regulator (YAP1) are used for sub-classification." (PMID 39937015, 2025). "It has been demonstrated that NEUROD1 expression is essential for the survival, proliferation, and migration of NEUROD1-positive small-cell lung cancers." (PMID 39858036, 2025). "Previous studies have shown that NeuroD1, originally discovered as a factor regulating neuronal development, is upregulated in several types of cancer, including neuroblastoma, small cell lung cancer, colon cancer, breast cancer, and pancreatic cancer." (PMID 38134213, 2023). "NEUROD1 has been identified as a subtype marker in neuroendocrine tumors, especially small-cell lung cancer." (PMID 36313290, 2022). "Several mechanistic investigations have shown that NEUROD1 effectors boost the survival, migration, and proliferation of small-cell lung cancer (SCLC) cells by activating cell surface receptor tyrosine kinase tropomyosin-related kinase B (TRKB) and neural cell adhesion factor (NCAM1)." (PMID 39858036, 2025). "In small-cell lung cancer, NEUROD1-dependent genes are specific targets of lurbinectedin." (PMID 36313290, 2022). "The classification of small cell lung cancer (SCLC) into distinct molecular subtypes defined by ASCL1, NEUROD1, POU2F3, or YAP1 (SCLC-A, -N, -P, or -Y) expression, paves the way for a personalized treatment approach." (PMID 38180245, 2024). "Background/Objectives: Small-cell lung cancer (SCLC) is a highly aggressive malignancy with an emerging molecular classification based on the expression of the transcription factors ASCL1, NEUROD1, and POU2F3." (PMID 39682568, 2024). "Several transcription factors in small cell lung cancer (SCLC), including achaete-scute homolog 1 (ASCL1) and neurogenic differentiation factor 1 (NEUROD1), contribute to rapid tumor growth and early metastatic dissemination." (PMID 37253435, 2023). "Small cell lung cancer (SCLC) is a recalcitrant malignancy defined by subtypes on the basis of differential expression of the ASCL1, NEUROD1, and POU2F3 transcription factors." (PMID 35612556, 2022). "Recent studies have reported that the subtypes of small cell lung cancer contained atonal bHLH transcription factor 1 (ATOH1), pOU class 2 homeobox 3 (POU2F3), neurogenic differentiation factor 1 (NEUROD1), and achaete–scute complex homolog-like (ASCL1)." (PMID 36551512, 2022). "We also wondered about the distribution of TRIT1 gene amplification according to the small-cell lung cancer molecular subtypes ASCL1, NEUROD1, POU2F3, and YAP1." (PMID 33919717, 2021). "(b) Heat map of the PEA3 family ETS transcription factors (ETV1, ETV4, and ETV5) and neuroendocrine transcription factors (ASCL1, NEUROD1, INSM1, and POU3F2 [BRN2]) in small cell lung cancer and lung adenocarcinoma cell lines." (PMID 34121659, 2021). "NEUROD1 is expressed in approximately 50% of small cell lung carcinoma cases; however, this expression is not universal." (PMID 39937015, 2025). "In small cell lung carcinomas, OTX2 was also associated with MYC activity, though this was regulated by NEUROD1 and not ASCL143." (PMID 39349591, 2024). "In small cell lung cancer cell lines, ecDNA containing MYC leads to amplification of MYC and cis-regulates the expression of NEUROD1, resulting in an expression pattern consistent with the NEUROD1 high expression subtype and sensitive to Aurora kinase inhibitors." (PMID 37217468, 2023).
small cell lung carcinoma (continued). "Small cell lung cancer (SCLC) has recently been characterized as heterogeneous tumors due to consensus nomenclature for distinct molecular subtypes on the basis of differential expression of four transcription markers (ASCL1, NEUROD1, POU2F3, and YAP1)." (PMID 35311069, 2022). "In small cell lung cancer (SCLC), ASCL1 and NEUROD1 could regulate various genes such as SOX2, MYCL1, that contribute to neuronal function and promote perineural invasion." (PMID 36376881, 2022). "Moreover, small cell lung cancer (SCLC) has been classified into four molecular subtypes, including ASCL1+, NEUROD1+, POU2F3+ and YAP1+ SCLC." (PMID 34722635, 2021). "Small-cell lung cancer (SCLC) is an aggressive malignant cancer that is classified into four subtypes based on the expression of the following key transcription and co-transcription factors: ASCL1, NEUROD1, YAP1, and POU2F3." (PMID 33202998, 2020). "For comparison, we also collected EVs secreted by a non‐small cell lung cancer cell line (A549) and human bronchial epithelial cells (HBEC) as negative controls, as these cells lack ASCL1, NEUROD1, and POU2F3 expression." (PMID 40285610, 2025). "Despite recent progress in subtype classification for small cell lung carcinoma (SCLC), little is known about the biomarker for triple‐negative (ASCL1, NEUROD1, and POU2F3 negative) tumors." (PMID 37789961, 2023).
type 2 diabetes (23 papers, 2012 to 2026). "Clinical characteristics of Chinese early‐onset type 2 diabetes patients with rare variants of NEUROD1." (PMID 40148250, 2025). "Mutations in the NEUROD1 gene in humans are linked to type 2 diabetes and a subtype of maturity-onset diabetes of the young (MODY6)." (PMID 39105169, 2024). "NEUROD1 (p.Glu59Gln) mutation identified in our study has been previously reported in maturity-onset diabetes in an Indian cohort." (PMID 33484326, 2021). "We identified heterozygous missense mutation in NEUROD1 (p.Glu59Gln) in one patient (P2), which was previously reported to be associated with maturity-onset diabetes of the young (MODY) phenotype in Indian population." (PMID 33484326, 2021). "Rare variants of NEUROD1 detected in Chinese early‐onset type 2 diabetes patients." (PMID 40148250, 2025). "firstly described two heterozygous NEUROD1 mutations in as many patients with type 2 diabetes." (PMID 35769090, 2022). "Additional pathways included maturity onset diabetes (NEUROD1 gene), collecting duct acid secretion (ATP4A), and various metabolic processes." (PMID 40725485, 2025). "Of note, mutations in subtype-defining transcription factors, including HNF1A, TCF4, NEUROD1 and HNF4A, cause MODY, and their cis-regulatory sites map to type 2 diabetes risk loci." (PMID 40768044, 2025). "Heterozygous mutations in NeuroD1 have been identified to be associated with maturity-onset diabetes (OMIM: 601724) and type 2 diabetes mellitus." (PMID 30359270, 2018). "Moreover, mir-24 has also been found to inhibit β-cell proliferation and insulin secretion by targeting maturity-onset diabetes of the young (MODY) genes, Hnf1α and Neurod1." (PMID 41384367, 2026). "In pancreatic islet cells from type 2 diabetic patients, miR-124a was highly expressed, and its silencing in MIN-6 cells resulted in increased expression of genes involved in insulin secretion, such as Mtpn, Foxa2, Sirt1, and NeuroD1." (PMID 30974824, 2019).
Alzheimer disease (18 papers, 2016 to 2026). A progressive, neurodegenerative disease characterized by loss of function and death of nerve cells in several areas of the brain leading to loss of cognitive function such as memory and language. "NEUROD1 has been reported to reprogram cultured human astrocytes in an Alzheimer’s disease mouse model into functional glutamatergic neurons." (PMID 41371337, 2025). "Recent works have demonstrated the conversion of reactive astrocytes to glutamatergic neurons through NeuroD1 delivery in a middle cerebral artery occlusion model and Alzheimer’s disease model using lentiviruses and retroviruses, respectively." (PMID 39014391, 2024). "This was successfully employed to drive expression of key proneural TFs for reprogramming, such as NeuroD1 and Dlx2, in mouse models of Alzheimer’s disease, Huntington’s disease, and ischemic brain injury." (PMID 36289861, 2022). "We have previously demonstrated successful astrocyte-to-neuron conversion in mouse brains with injury or Alzheimer's disease by overexpressing a single neural transcription factor NeuroD1." (PMID 33425896, 2020). "Our group has previously demonstrated that the neurogenic transcription factor NeuroD1 can reprogram reactive astrocytes into functional neurons in the stab-injured brain and in a mouse model for Alzheimer's disease." (PMID 33425896, 2020). "Accordingly, it has been recently demonstrated that by enhancing the differentiation of dentate gyrus progenitor cells through NeuroD1 overexpression it is possible to counteract the memory defects in a mouse model of Alzheimer’s disease." (PMID 28740463, 2017). "Additionally, the signatures of several transcription factors, such as Olig2, NeuroD1, TCF4, and NeuroG2, were found to be enriched in Alzheimer’s disease-associated accessible chromatin regions within hippocampal tissues." (PMID 40483385, 2025). "Taking two brain-injury cases—including stab-injured brain and Alzheimer’s disease (AD) brain tissue—another report enrolling NeuroD1 showed an efficient transdifferentiation of glia/astrocytes and NG2 cells into the functional and mature neurons in mouse brain." (PMID 34685537, 2021). "While stab injury model has been commonly used in various in vivo cell conversion studies, we have previously demonstrated in a mouse Alzheimer’s disease model that NeuroD1 can convert reactive astrocytes into functional neurons in 14-month old AD mouse brains." (PMID 33224952, 2020). "Another surprising finding about NeuroD1 is that even in 14-month old Alzheimer’s disease mouse model (5xFAD), NeuroD1 can still efficiently convert reactive astrocytes into functional neurons, characterized by highly functional electrophysiological properties." (PMID 30872991, 2019). "We found that environmental enrichment greatly affects the expression of markers specific for stem cells, progenitor cells and differentiated neurons (Pax6, Ngn2, NeuroD1, NeuN) in the hippocampus of young adult rats or rats with Alzheimer’s disease (AD) model but less efficiently in aged animals." (PMID 28798684, 2017). "In addition, it is reported in the literature that reactive glial cells in the cortex of stab-injured or Alzheimer's disease (AD) model mice can be directly reprogrammed into functional neurons in vivo using retroviral expression of NeuroD1." (PMID 27078155, 2016). "Finally, using the viral-mediated overexpression of the pro-neurogenic transcription factor Neurod1 in newborn granule neurons observed an increase in neurogenesis at the expense of gliogenesis, and a rescue of memory performances in a mouse model for Alzheimer’s disease (AD)." (PMID 30538622, 2018).
Stroke (17 papers, 2019 to 2025). Sudden impairment of blood flow to a part of the brain due to occlusion or rupture of an artery to the brain. "Collectively, these findings provide evidence that cell reprogramming with NeuroD1 can modulate the neuroinflammatory response associated with stroke and impact functional recovery in a canine model." (PMID 41541863, 2025). "NeuroD1 has been reported as a critical regulator of neuronal development, during which it promotes neurogenesis and the migration of newborn neurons by directly modulating the underlying transcriptional program, which is beneficial for stroke recovery." (PMID 33584204, 2020). "Previous studies selected acute or early subacute rodent stroke models to conduct NEUROD1‐mediated in vivo AtN conversion and demonstrate that it can promote both the tissue repair and functional recovery." (PMID 40401537, 2025). "Herein, we have demonstrated that the AAV5-mediated expression of Neurod1 driven by the shGFAP promoter leads to post-stroke functional recovery." (PMID 38540276, 2024). "AAV5::Neurod1 or AAV5::Cre control was injected into the injured cortex of Cre-conditional reporter mice (R26R-YFP or R26R-tdTomato) on post-stroke day 7 (PSD7), a time that reflects the subacute phase of injury." (PMID 38540276, 2024). "Chen and colleagues examined the effects of ectopic expression of Neurod1 following stroke and reported similar outcomes while highlighting some important considerations for stroke studies." (PMID 38540276, 2024). "In this study, our 9-week timeline exceeding this recommendation is considered chronic in terms of rodent stroke models, and importantly, it was still able to detect deficits in untreated controls that were significantly improved in Neurod1-treated animals." (PMID 38540276, 2024). "We compared the brains of stroke-injured Neurod1 and Cre-injected animals at PSD63 and found similar lesion volumes (stroke/Neurod1 = 0.06 ± 0.03 mm3; stroke/Cre = 0.07 ± 0.01 mm3; p = 0.62)." (PMID 38540276, 2024). "We analyzed the expression of neuronal subtype-specific transcription factors CUX1 (upper-layer neurons, layers 2/3) and CTIP2 (lower-layer projection neurons, layers 5/6) at PSD63 in R26R-YFP mice that received Neurod1 post-stroke." (PMID 38540276, 2024). "Stroke-injured mice that received Neurod1 or Cre in the stroke-injured cortex on PSD7 were assessed for motor function using the grid walk task at PSD28 and CatWalk for gait analysis at PSD63." (PMID 38540276, 2024). "Stroke-injured mice displayed a significant motor deficit on the grid walking task at PSD4 prior to treatment with Cre or Neurod1 (p = 0.003, p = 0.002, respectively)." (PMID 38540276, 2024). "By PSD28, only mice that received Cre were recovered to baseline performance [stroke/Neurod1 = 0.22 ± 0.53 slips (p = 0.846); stroke/Cre = 1.58 ± 0.26 slips (p = 0.005); sham/Cre, 1.91 ± 0.37 slips (p = 0.0004); uninjured controls, −0.15 ± 0.34 slips]." (PMID 38540276, 2024). "We predicted that perilesional reactive astrocytes would be transduced following stroke and Neurod1 treatment." (PMID 38540276, 2024). "Here, we demonstrate that ectopic expression of Neurod1 is sufficient for functional improvement following sensory–motor stroke." (PMID 38540276, 2024). "We used an adeno-associated virus to deliver Neurod1 from the short GFAP promoter and demonstrated improved functional outcomes as early as 28 days post-stroke and persisting to at least 63 days post-stroke." (PMID 38540276, 2024). "Using the grid walk task and gait analysis, we demonstrate that ectopic expression of Neurod1 in the stroke-injured brain leads to functional improvement as early as three weeks post Neurod1 delivery and that the recovery is sustained long-term." (PMID 38540276, 2024). "Overall, our findings indicate that ectopic expression of Neurod1 in the stroke-injured brain is sufficient to enhance neural repair." (PMID 38540276, 2024).